HMGB1 (high mobility group box 1)
Diseases named in the same sentence as HMGB1 in open-access papers (continued):
Sharing a sentence is not in itself a finding about the gene and the disease.
melanoma (continued). "In murine models of colon cancer and melanoma, lysis of tumors by injection of IL PV-10 led to the release of HMGB1, dendritic cell (DC) maturation and migration into tumor-draining LNs, and the induction of CD8+ T cells that recognize tumor." (PMID 29694419, 2018). "In this regard, in a previous study, we have shown that HS conditioning is able to induce the secretion of the DAMP protein HMGB1 by melanoma cells as well as the mobilization of CALR to plasma membrane, a well-known “eat me” signal for phagocytic cells." (PMID 29744371, 2018). "The previous studies have shown that UV irradiation-damaged skin cells produce HMGB1 that recruits and activates neutrophils, promoting angiogenesis and melanoma metastasis." (PMID 30292233, 2018). "In melanoma patients, treatment with IL PV-10 also results in increased serum HMGB1 levels and improved anti-tumor activity of circulating CD8+ T cells." (PMID 29694419, 2018). "Using a combination of GEMM and transplant models of melanoma, UV radiation was shown to promote neutrophil infiltration through secretion of high-mobility group protein B1 (HMGB1) derived from UV-damaged keratinocytes." (PMID 28883015, 2017). "Immunohistochemical analysis showed that integrin-β1 expression was found in both S100+/HMGB-1+ melanoma cells and fibroblasts within the matrices." (PMID 28476030, 2017). "In a cell-specific fashion, melanoma isolates released the immunogenic protein HMGB1 into the extracellular environment." (PMID 29137331, 2017). "This suggests that treatment of melanoma cells with PV-10 leads to the release of HMGB1, and the activation of DCs." (PMID 27177220, 2016). "In conclusion, our study first proposed that inflammation inhibits Klotho gene expression in melanoma cells through activation of the inflammatory mediators Hmgb1 and NF-κB signal pathway." (PMID 27779100, 2016). "Collectively, our findings identify a mechanism by which hypoxia affects tumour growth and metastasis in melanoma and depict HMGB1 as a potential therapeutic target." (PMID 27426915, 2016). "The induction of HMGB1 expression by hypoxia in melanoma cells in culture was only significantly induced after 72 hours of hypoxia, but not at shorter exposure times to hypoxia." (PMID 27426915, 2016). "Experiments with two melanoma cell lines showed that both Hmgb1 protein and LPS treatment increased the malignant phenotypes of melanoma cells via activation of NF-κB." (PMID 27779100, 2016). "This study showed that silencing Hmgb1 expression significantly increased the percentage of G0/G1 cells and apoptosis in melanoma cells, and reduced tumor cell invasion." (PMID 27779100, 2016). "We have recently addressed the role of HMGB1 in the context of the innate immune response against tumors by investigating the function of this protein in the NK:melanoma cell interaction and in the subsequent NK-mediated killing of tumor cells." (PMID 27294158, 2016). "Here, we show that hypoxic melanoma cells release the alarmin HMGB1, which promotes tumour growth and metastasis through the accumulation, within tumours, of TAMS bearing an M2-like phenotype." (PMID 27426915, 2016). "In conclusion, we demonstrate that HMGB1, derived from hypoxic tumour cells, significantly contributes to melanoma progression by favouring the accumulation of IL-10-secreting TAMs within the tumour." (PMID 27426915, 2016). "In conclusion, Hmgb1 can inhibit Klotho gene expression and malignant phenotype in melanoma cells through activation of NF-κB signaling." (PMID 27779100, 2016). "In this study, we showed that IL PV-10 led to the necrosis of melanoma cells and the release of HMGB1." (PMID 27177220, 2016). "Significantly, increased levels of HMGB1 were found in the serum of patients with metastatic melanoma when compared to patients with primary melanoma and to healthy donors." (PMID 27426915, 2016).
melanoma (continued). "This study investigated the effects of Hmgb1 and LPS on Klotho gene expression in melanoma cells and their relationship with NF-κB signaling and the biological significance of inflammation-Klotho in the malignant phenotype of melanoma." (PMID 27779100, 2016). "Co-labelling with an anti-melanosome antibody (clone HMB-45) showed that, in metastasis, HMGB1 is released by HMB-45+ melanoma cells in contrast to primary tumours where HMGB1 was exclusively found in the nucleus of HMB-45+ melanoma cells." (PMID 27426915, 2016). "Introduction of exogenous Hmgb1 significantly decreased apoptosis, increased invasion, elevated p-NF-κB, but lowered Klotho protein level in melanoma cells." (PMID 27779100, 2016). "Altogether, these results suggest that HMGB1 released by hypoxic tumour cells promotes melanoma growth and metastasis." (PMID 27426915, 2016). "In contrast, administration of exogenous Hmgb1 decreased apoptosis and the percentage of G0/G1 cells, and increased cell invasion and NF-κB phosphorylation in the melanoma cells." (PMID 27779100, 2016). "Our previous studies demonstrated that Hmgb1 is highly expressed in melanoma tissues, and is a predictive factor for the poor prognosis of melanoma patients." (PMID 27779100, 2016). "In melanoma-bearing mice, IL PV-10 induced necrosis of tumor cells leading to the release of HMGB1, which is crucial for DC activation." (PMID 27177220, 2016). "HMGB1 was measured in the supernatants of B16, primary melanomas, and 888 cells in a dose-dependent manner." (PMID 27177220, 2016). "Another study on melanoma cells treated with lymphokine-activated killing cells led to detectable HMGB1 levels in cell culture supernatant as early as 4 to 24 h." (PMID 26854151, 2015). "In a HMGB1 knockdown in melanoma, a marked decrease in cell proliferation was observed mediated by p21 in a SP1 dependent manner." (PMID 26405815, 2015). "Necroptosis was inducible in poorly immunogenic B16-F10 melanoma cells and zVAD-fmk generally increased melanoma cell necrosis concomitantly with the release of HMGB1." (PMID 25973681, 2015). "Fostering melanoma cell necrosis with zVAD-fmk increased the amount of HMGB1 in the SNs of the tumor cells." (PMID 25973681, 2015). "When compared with normal skin and nevi tissues, there was a significantly elevated expression of HMGB1 detected in the majority of the melanoma specimens." (PMID 25051367, 2014). "Here, we reported for the first time that high levels of HMGB1 in melanoma correlate with advanced disease stages and poor patient survival." (PMID 25051367, 2014). "We took the advantage of the different levels of knockdown by the sequence #1 and #2 (sh-1 & sh-2) for assessing a dosage-dependent contribution of HMGB1 to melanoma cell proliferation." (PMID 25051367, 2014). "We addressed this need by analyzing the expression of HMGB1 using immunohistochemistry in 102 cases of human melanoma." (PMID 25051367, 2014). "Immunohistochemistry analysis of the tumor sections showed an inverse correlation of HMGB1 and p21 expression in that HMGB1-knockdown melanoma tumors expressed elevated level of p21." (PMID 25051367, 2014). "The results again indicated a dose-dependent effect of HMGB1 in regulation of melanoma cell proliferation, higher levels of HMGB1 expression correlated with high rates of cell proliferation." (PMID 25051367, 2014). "An absolute dependency of melanoma cell proliferation on HMGB1 was underscored by the marked response of cell cycle arrest and senescence to HMGB1 knockdown." (PMID 25051367, 2014). "We sought to link the distribution of the HMGB1 protein to its oncogenic activity observed in human melanoma." (PMID 25051367, 2014). "A close examination of melanoma patient samples discovered that the HMGB1 protein was mainly localized inside the cancer cells, suggesting an activity mediated by the intracellular HMGB1 at work in human melanoma." (PMID 25051367, 2014).
melanoma (continued). "In summary, we uncovered that HMGB1 was highly overexpressed in melanoma samples when compared with normal skin and nevi tissues." (PMID 25051367, 2014). "The melanoma xenograft data together provided in vivo evidence indicating a crucial role of HMGB1 in promoting melanoma cell proliferation and progression." (PMID 25051367, 2014). "Unlike the well-documented pro-inflammatory role of the extracellular HMGB1, we found that its intracellular activity is necessary for melanoma cell proliferation." (PMID 25051367, 2014). "Analysis of the expression data with the melanoma stage uncovered a clear positive correlation between the disease stage and the level of HMGB1 expression, as reflected by markedly higher HMGB1 protein levels detected in the more advanced stages of melanoma." (PMID 25051367, 2014). "A crucial role for HMGB1 in melanoma development was demonstrated by the finding that depletion of HMGB1 expression resulted in considerable suppression of melanoma tumor development." (PMID 25051367, 2014). "The mechanism of LTX-315 is thought to be similar to that of LTX-302, by inducing long-term, specific cellular immunity against B16 melanomas through membrane-induced lysis and the extracellular release of DAMPs (HMGB1)." (PMID 24676901, 2014). "The induction of cell cycle arrest and senescence is consistent with the decreased rate of cell proliferation in HMGB1-knockdown melanoma cells." (PMID 25051367, 2014). "Taken together, our data demonstrate a novel oncogenic role of HMGB1 in promoting human melanoma cell proliferation and have important implications in melanoma patient care." (PMID 25051367, 2014). "The Kaplan-Meier curve of HMGB1 levels and patient outcomes revealed a significant correlation of the level of HMGB1 expression and melanoma patient survival." (PMID 25051367, 2014). "To gain a better understanding of how HMGB1 contributes to melanoma cell proliferation, we examined cell cycle progression." (PMID 25051367, 2014). "In support of a crucial role of HMGB1 in melanoma cell proliferation, we demonstrated that decreased expression of HMGB1 via RNAi-mediated knockdown resulted in considerably reduced rate of cell proliferation." (PMID 25051367, 2014). "Measurement of cell growth curve revealed a critical role of HMGB1 in supporting melanoma cell proliferation." (PMID 25051367, 2014). "To further explore the connection between HMGB1 with the progression of human melanoma, we examined the status of cell proliferation by measuring the mitotic index." (PMID 25051367, 2014). "The mechanistic data are consistent with a role of nuclear HMGB1, in line with our observation of its being chiefly nuclear localized in human melanoma cells." (PMID 25051367, 2014). "A potential contribution of HMGB1 to melanoma has been suggested from preclinical studies, but awaits further validation with the clinical evidence." (PMID 25051367, 2014). "Significantly, higher levels of HMGB1 correlated with more advanced disease stages and with poorer survival in melanoma patients." (PMID 25051367, 2014). "In line with this notion was the finding that melanoma cells underwent cell cycle arrest and senescence upon depletion of HMGB1 expression." (PMID 25051367, 2014). "Our data together provide much needed clinical evidence supporting an oncogenic role of HMGB1 in human melanoma." (PMID 25051367, 2014). "Melanoma cells treated with LTX-315 showed a gradual translocation of HMGB1 from the lysate to the supernatant after peptide treatment, with an increasing concentration in the supernatant as time progressed." (PMID 24676901, 2014). "Consistent with a crucial role of HMGB1 in promoting melanoma cell proliferation, a positive correlation between HMGB1 expression and cell proliferation was observed." (PMID 25051367, 2014). "We showed that HMGB1 is crucial in melanoma cell proliferation because HMGB1 depletion leads to a dramatic inhibition of melanoma cell proliferation both in vivo and in vitro." (PMID 25051367, 2014).
melanoma (continued). "The results implicate that human melanoma cells depend on the expression of HMGB1 for the ability to proliferate." (PMID 25051367, 2014). "In our further study, blockade of Hmgb1-RAGE pathway inhibits melanoma tumor growth and reduces production of IL-23 and IL-17." (PMID 24453427, 2013). "This study reveals a crucial role for the Hmgb1-IL-23-IL-17-IL-6-Stat3 axis in the development of melanoma." (PMID 24453427, 2013). "Although further investigations are needed to fully clarify the precise molecular and cellular mechanism involved in the immunoregulation, Hmgb1-IL-23-IL-17-IL-6-Stat3 axis contributes to tumor growth in murine models of melanoma." (PMID 24453427, 2013). "In melanoma, HMGB1 is overexpressed in tumor compared to normal melanocyte, leading to malignant transformation and melanoma development." (PMID 22496788, 2012). "The secretion of HMGB1 has been reported in the cells of several malignancies including glioma, colon cancer, lung cancer, and melanoma." (PMID 22496788, 2012). "Furthermore, treatment with Mn-ZIF-8 in combination with IR (6 Gy) enhanced the release of HMGB1 from the cell nuclei as well as ATP production in B16 and A375 melanoma cells." (PMID 40585994, 2025). "HMGB1 is secreted by melanoma tumor cells as a consequence of hypoxia, and could increase M2-like TAMs accumulation and an create an IL-10-rich TME." (PMID 39703508, 2024). "HMGB1 has a significant role in the growth and spread of murine melanoma." (PMID 39703508, 2024). "Primarily used in the treatment of solid tumors such as melanoma, CIRT promotes tumor immunogenicity by enhancing the translocation of calreticulin to the plasma membrane, enhancing the release of HMGB1 and ATP, and promoting an IFN1 response, all major hallmarks of ICD." (PMID 37626741, 2023). "Additionally, high-mobility group box 1 (HMGB1), a damage-associated molecular pattern (DAMP) released during melanoma treatment with targeted therapy, can also initiate inflammasomes in melanoma cells." (PMID 37373523, 2023). "Interestingly, HMGB1 has been shown to be secreted at high levels in hypoxic conditions in glioblastomas and melanomas, resulting in tumor growth and metastasis." (PMID 37627239, 2023). "In addition to the cytotoxicity against melanoma cells, NK cells promote their recruitment via High Mobility Group Box-1 (HMGB1) protein." (PMID 36434591, 2022). "The attenuated poliovirus (PV)-based vector PVSRIPO, which has its Internal Ribosomal Entry Site (IRES) substituted with IRES from rhinovirus type 2 (HRV2) to eliminate PV’s neurovirulence, was shown to induce HSPs, HMGB1, viral dsRNA, and tumor antigen release from melanoma and breast cancer cells." (PMID 36755812, 2022). "All these findings demonstrated that miR-548b might act as a cancer-suppressive miRNA in human melanoma by inhibiting HMGB1, thus suggesting potential systemic and local usefulness." (PMID 36012593, 2022). "It has been hypothesized that HMGB1 knockout in melanoma cells may suppress tumor growth in vivo via CD8+ T cells and accelerate the infiltration of CD8+ T cells, macrophages, and the activation of dendritic cells resident in tumor tissues." (PMID 36012593, 2022). "In a mouse model, PDT treatment with ML19B01 and ML19B02, two structurally related ruthenium photosensitizers, induced death of melanoma cells containing hallmarks of the ICD including HMGB1, which in turn activated antigen-presenting cells resulting in efficient phagocytosis by dendritic cells." (PMID 36012593, 2022). "Interestingly, elevated levels of HMGB1 positively correlated with several clinicopathological features of melanoma, among them tumor thickness, mitotic index, and metastases." (PMID 36012593, 2022). "HMGB1 is a target of miR-548b, and its expression level is negatively regulated by miR-548b, while the reintroduction of HMGB1 abolishes the inhibiting effects of miR-548b on melanoma cells." (PMID 36012593, 2022).
melanoma (continued). "Furthermore, recent studies demonstrate that oncolytic NDV caused CALR exposure, HMGB1 and HSP70/90 release, as well as ATP secretion, resulting in ICD induction in melanoma cells." (PMID 35488303, 2022). "Furthermore, melanoma patients with diagnosed metastatic tumor exhibited elevated serum concentration of HMGB1." (PMID 33918883, 2021). "Interestingly, we found that Salmonella treatment on melanoma cells triggered an increased secretion of HMGB1." (PMID 34207850, 2021). "Moreover, Salmonella treatment increased HMGB1 secretion in melanoma, and the increased extracellular HMGB1 facilitated macrophage polarization into the M1-like phenotype, an inflammation-related mechanism tapped by Salmonella to further prevent metastasis." (PMID 34207850, 2021). "In hypoxia, melanoma cells have been shown to release higher levels of HMGB1 than in normoxia." (PMID 34360919, 2021). "Indeed, miR-26a re-expression sensitized melanoma cell lines to dabrafenib, targeting the high mobility group box 1 (HMGB1)-dependent autophagy, and finally, engaging the apoptosis program." (PMID 34209162, 2021). "Moreover, HMGB1 facilitated ALO mediated melanoma cell apoptosis by binding to its receptor, Toll-like receptor 4 and activating extracellular regulated protein kinases (ERK) signal pathway." (PMID 32536835, 2020). "Altogether, these studies suggested that HMGB1 is a critical protein and may be considered as a novel therapeutic target in melanoma." (PMID 32536835, 2020). "However, the depletion of HMGB1 with shRNA in mice with B16 melanoma cells-derived tumor significantly reduced tumor growth and the amount of TAMs." (PMID 32486098, 2020). "A previous study reported that HMGB1 recruits neutrophils to promote melanoma progression." (PMID 32943604, 2020). "Indeed, the HMGB1/RAGE axis was found to influence melanoma tumor growth through the expression of IL-23 and IL-17 from a sub-population of T cells, (gdT cells), resulting in the activation of STAT-3 in a IL-6 dependent manner." (PMID 33256110, 2020). "To assess the effect of mEHT on the secretome of the melanoma tumor, we isolated tumor interstitial fluid (see the Methods section) 48 h after the third mEHT treatment, which we used to detect the amount of hsp70, HMGB1 proteins, and ATP." (PMID 31426515, 2019). "Additionally, in a melanoma mouse model it was observed that HMGB1 release promoted M2 macrophage recruitment and IL10 expression and was associated with tumor growth and metastasis." (PMID 29472602, 2018). "Moreover, NK cells, upon interaction with melanoma cells, can release a chemotactic form of HMGB1 protein that is capable of attracting additional activated NK cells." (PMID 29190907, 2017). "Thus, both AR42 and sodium valproate also likely have the capacity to immunologically compromise mutant B-RAF melanoma cells and other tumor cell types via HMGB1 release." (PMID 29137331, 2017). "In this study, 4 melanoma cell lines were used to screen Klotho and Hmgb1 protein expression." (PMID 27779100, 2016). "We have shown that, during the interaction with melanoma cells, NK cells could release an HMGB1 form endowed with chemotactic activity, while killed melanoma cells passively released an oxidized, nonchemotactic form of HMGB1." (PMID 27294158, 2016). "Indeed, recent studies have provided evidence for a role of HMGB1 in the induction of the EMT, while in our lab we have recently shown that HMGB1 is actively released during NK:melanoma cell interaction and can amplify recruitment of NK cells." (PMID 27294158, 2016). "The exceptional ability of ApoV to protect against melanoma challenge could relate to products of “immunogenic cell death”, such as high mobility group box protein B1 (HMGB1) and calreticulin translocating to the ApoV pathway." (PMID 27462921, 2016). "Finally, we show that HMGB1 has an important role in murine B16 melanoma growth and metastasis, whereas in humans its serum concentration is significantly increased in metastatic melanoma." (PMID 27426915, 2016).